CCL21 (C-C motif chemokine ligand 21)
Diseases named in the same sentence as CCL21 in open-access papers (continued):
Sharing a sentence is not in itself a finding about the gene and the disease.
infection (60 papers, 2009 to 2026). The state of being infected such as from the introduction of a foreign agent such as serum, vaccine, antigenic substance or organism. "If these findings reflect that CCL19 and CCL21 not only carry out their homeostatic role, but also play a pathogenic role in these infections, this should be examined in forthcoming studies." (PMID 24507453, 2014). "The findings showed that the co-delivery of the γ-Flu vaccine and CCL21 or Poly (I:C) significantly increased the vaccine immunogenicity compared to the non-adjuvanted vaccine, associated with more potent protection following challenge infection." (PMID 34627297, 2021). "Moreover, in experimental murine R. conorii infection increased expression of CCL19 and CCR7 and in particular, CCL21 was associated with lethal infection." (PMID 24507453, 2014). "Moreover, mice deficient for the gene encoding CCL21 have greater susceptibility to infection when exposed to L. donovani due to the loss of dendritic cell migration." (PMID 22506080, 2012). "As early as 24 h post-infection, CCL21 was strongly downregulated as detected by immunofluorescent microscopy (IFM)." (PMID 39708807, 2025). "To mimic a local infection scenario, we tested the effect of subcutaneous lymphocytic choriomeningitis virus (LCMV) footpad infection on CCL21 expression in the draining popliteal LN (pLN)." (PMID 39708807, 2025). "Previous reports have shown that CCL21 expression decreases in various infection models, with strong downregulation after systemic infection with type-1 response-inducing pathogens after 7–8 days." (PMID 39708807, 2025). "Taken together, these results suggest that CCL21 suppression during infection leads to an increased dependence on oxysterol-EBI2 for lymphocyte homing to draining LNs." (PMID 39708807, 2025). "When we performed short-term transfers, pLNs from mice given CCL19 showed EBI2−/− B cells homing at nearly the same level as WT-transferred B cells, thus reversing the effect of infection-induced CCL21 downregulation." (PMID 39708807, 2025). "CCL21 protein and mRNA remained low at day 3 post-infection, and Cxcl12 and Cxcl13 were also repressed." (PMID 39708807, 2025). "The gene expression of the chemokines involved in T cell and B cell recruitment, Ccl21 and Cxcl13 were both significantly increased in the salivary glands during LucAdV5 infection compared to uninfected tissue." (PMID 39355243, 2024). "Our data reveal a previously unrecognized mechanism regulating the integrity of the stromal network expressing the T cell–homing chemokine CCL21 during infection." (PMID 36317628, 2022). "Together, these data suggest that the translocation of CD35+ FDC clusters and B cells into the paracortex following infection contributes to the displacement of CCL21-expressing FRCs and T cells in this region." (PMID 36317628, 2022). "CCL21 ranked as the most downregulated gene with a 16-fold downregulation in H37Rv infection as compared with the other two conditions." (PMID 34276658, 2021). "TLR7 and CCL21 were the only two downregulated genes following H37Rv infection with respect to the uninfected controls." (PMID 34276658, 2021). "In contrast, significant upregulation of both SPARC and CCL21 mRNA was observed after infection with live parasites." (PMID 33633185, 2021). "Using RT-qPCR, we found a significant increase in the gingival expression of CCL19 and CCL21 of WT upon infection." (PMID 29967614, 2018). "The RP2D of the combination vaccine was 7.5 × 106 irradiated H1944 adenocarcinoma cells expressing CCL21 (multiplicity of infection of 500), 7.5 × 106 irradiated H2122 adenocarcinoma cells, and 15 × 106 GM.CD40L cells (1.1 mL)." (PMID 30209589, 2018). "Relevant to our naïve CD4+ T cells findings, the DLNs from old mice had nearly a 10-fold decrease in the naïve T cell chemoattractant CCL21 at day 2 after infection." (PMID 26204259, 2015). "Expression of the B cell chemoattractants CXCL13, CCL19 and CCL21 increased progressively post infection." (PMID 24847941, 2014).
infection (continued). "In one study, DCs transduced with adenoviral CCL21 (AdCCL21) at multiplicities of infection (MOIs) of 50:1 or 100:1 were able to produce up to 210 ± 9 ng/mL and 278 ± 6.5 ng/mL human CCL21 per 106 cells per 48 h in vitro, respectively." (PMID 24810425, 2014). "Conversely, there was no significant increase in mRNA expression of CCL5, CCL19, CCL20 and CCL21 chemokines after infection in both MyD88+/+ and MyD88−/− mice." (PMID 23374751, 2013). "Impaired CCL21 production correlates with a loss of MZM and reduced pathogen clearance after infection by Leishmania donovani." (PMID 23194300, 2012). "Since CCR7 was expressed at high levels on brain DCs, the expression of the chemokine CCL21 (ligand for CCR7) was elevated during infection, and CCR7 on the brain DCs was functional in in vitro chemotaxis studies, this receptor was first targeted." (PMID 21949652, 2011). "These include TLR-induced pro-inflammatory cytokine expression, DC migration in response to the chemokine, CCL21, and, importantly, DC-mediated capture of infectious virus particles and trans-infection of CD4+ T cells." (PMID 20617179, 2010). "Interestingly, two previous studies reported that during infection, CCL21 levels are profoundly downregulated in the spleen and in LNs, both at the protein and at the mRNA level." (PMID 41591762, 2026). "Interestingly, in one cohort study, the presence of antibodies against specific chemokines (CCL21, CXCL13 and CXCL16) was negatively associated with the development of LC at 1-year post-infection." (PMID 37445634, 2023). "Furthermore, tertiary lymphoid structure development in different organs is correlated with CCL21 ectopic expression in infection and autoimmunity." (PMID 35874608, 2022). "However, prior to and three days after infection, the levels of CCL21 in the lung and MLN were equivalent between developmental exposure groups." (PMID 30412605, 2018). "Various repressors of apoptosis such as Ilf3, Zmym2, Satb1, Ccl21 and Scd were downregulated and expression levels of inducers of apoptosis such as Daxx, Oas1, Lcn2 and Gng2 were upregulated with V3000 infection at 24 h pi resulting in an overall activation of the apoptotic pathway." (PMID 28446152, 2017). "By preventing DC migration in response to CCL21, PPARγ and LXR ligands may help to block the dissemination of DC-associated virus from mucosal sites of infection to regional lymph nodes." (PMID 20617179, 2010). "Indeed, the evolutionarily conserved pyrogenic response to infection is known to stimulate the immune response partly by promoting lymphocyte transendothelial migration across HEVs via increased luminal display of CCL21 (and ICAM1) under the influence of IL6 trans-signaling." (PMID 41216593, 2025). "CCL21 is a homeostatic chemokine ligand implicated in TB protection due to its assistive role in tertiary lymphoid follicles formation in lungs which helps in proper granuloma organization and accumulation of antigen-specific IFN-γ producing T-cells at the site of infection." (PMID 31681272, 2019). "Key amongst these chemokines are CCL21 and CXCL13, which are required for normal T zone and follicle segregation and 24 h after STm infection changes in expression of these chemokines have been reported." (PMID 36950118, 2023). "We observed that SP600125 promoted the expression levels of IL-6, CCL21, IFN-β, MX, and OASL, but the expression level of IL-1β decreased in DEF cells in the presence of CHa strain infection." (PMID 35837399, 2022). "Since CCL19 and CCL21 are the unique ligands for CCR7, contributing to DC migration into the dLN, we treated mice with CCL19- and CCL21-neutralizing Abs prior to infection and subsequently measured bacterial burdens in dLN." (PMID 36618364, 2022). "Reportedly, chemokines are specialized in the recruitment of various cells, including neutrophils (IL-8), monocytes (CCL2), Th1 cells (CXCL9, CXCL10), Th2 cells (CCL17, CCL21), and Th17 cells (CCL20), to sites of infection." (PMID 32231137, 2020).
infection (continued). "CCR1, 2, 3, 4, and CCL21 and 23 were all decreased in abundance in response to Makona and RESTV infection." (PMID 31689981, 2019). "For instance, upon infection, the reactivated T cells will secrete abundant IFN-r, which will induce the down-regulated expressions of CCL21 and CCL19, and thereby down-regulate the immune response of T cells upon the next infection." (PMID 26161081, 2015). "In contrast, expression of the B cell, T cell and DC chemoattractants CCL19 and CCL21 increased progressively to 7 days post infection with CCL19 elevated at day 1 and rising before CCL21." (PMID 24847941, 2014). "Some other genes such as CCL21, CXCR4, CCR1 and CCR7 exhibited a gradual increase during the infection." (PMID 22905138, 2012). "Changes in these structures have been reported in some infections, such as challenge with LCMV, where there is destruction of the FRC network and down-modulation of CCL21." (PMID 19578440, 2009). "Hypothetically, these chemokines may contribute to TB control by attracting monocytes to the site of infection via CCL2 and antigen-engaged B cells and central memory T cells via CCL19 and CCL21, respectively." (PMID 40458184, 2025). "The increase in EBI2’s homing role was not as large as occurring after infection, perhaps due to incomplete CCL21 blocking and lack of Ch25h upregulation." (PMID 39708807, 2025). "Chemokines and their GPCRs, such as CCL21 and CCR7, are not only important mediators of innate and adaptive immune responses in acute inflammation or infection, but also are continuously fine-tuning an immunological homeostasis, balancing immunity and tolerance." (PMID 36904259, 2023). "In monocytes or macrophages, SP600125 treatment also promoted the expression levels of IFN-β, MX, and OASL, but not CCL21, under CHa strain infection." (PMID 35837399, 2022). "Instead, transcripts for CCR7, the receptor for CCL19 and CCL21, were significantly lower in males compared to females in the late stage of HN878 infection, indicating reduced recruitment of DCs and/or T cells to the site of infection." (PMID 32198367, 2020). "Indeed in mouse lymphoid tissue specifically the homeostatic chemokines CCL19, CCL21 and CXCL13 were downregulated after infection with several different pathogens leading to altered homing, positioning and priming of lymphocytes within the LN61." (PMID 29379035, 2018). "In fact, upon infection the induced-expression of CXCL13 together with other chemokines, such as CCL21 and CCL19, could be indispensable to induce ectopic GC development." (PMID 26771137, 2016). "Our data shows that this process may be supported by infection-induced depression of dendritic-cell expressed CCR7 and reduced migration towards CCL21-dependent gradients." (PMID 26515292, 2015). "Increased CXCL13 expression from day 1 post infection preceded increased CCL19 and CCL21." (PMID 24847941, 2014). "In any case, results of this study have clearly demonstrated that upon MVA-B infection, bystander and viable MDDC are able to capture HIV antigens and, after full maturation, are able to migrate toward a gradient of CCL19 and CCL21, thus they would be competent to reach secondary lymphoid organs." (PMID 21625608, 2011). "Multiple biopsies (n = 5) from healthy lung allografts without infection or rejection demonstrated that CCL21 protein is predominately expressed from bronchiolar epithelial cells and alveolar macrophages." (PMID 20613873, 2010). "Thus, while the balance between the chemokines CCL21 and CCL3 changes during infection, the receptors for these chemokines, CCR7 and CCR5 respectively, are not altered on the naive T cells in the absence of cognate antigen." (PMID 19578440, 2009). "Therefore, mRNA levels for CCL21 and CCL3 within the lymph node, during infection were measured by RT-PCR." (PMID 19578440, 2009).
infection (continued). "Moreover, CCL2, CCL21, CXCL2, CXCR2, and CXCR3 mRNAs were significantly induced at 6–12 h after V. harveyi infection, implying that P. leopardus immune cells can be activated and recruited to the sites of infection at early time points post-infection." (PMID 39450165, 2024). "Indeed, CD4+ T-cell migration in the chronically infected brain parenchyma is CCL21-dependent, and infection is not controlled in the absence of CCL21." (PMID 22533989, 2012). "As expected, none of the mice in the CCL21, Poly (I:C), and PBS groups survived; all died between days 12 and 14 post-infection." (PMID 34627297, 2021). "Altogether, these data support infection-induced production of SPARC and CCL21 by astrocytes, but that neither SPARC nor CCL21 coat the fibrous SHG network." (PMID 33633185, 2021). "To further confirm the residency nature of most of the cervical cells supporting infection, we stimulated 10 day-infected tissue blocks with CCL19, CCL21, and S1P overnight to attract non-TRM out of the tissue in a transwell migration assay." (PMID 31628331, 2019). "On the other hand, the levels of CCL17, CCL21 and CCL22 were not affected by FusOn-H2 infection, and CCL5 was actually reduced by the virus treatment." (PMID 25460506, 2015).
inflammation (4 papers, 2021 to 2026). Aberrant reaction of the microcirculation characterized by movement of fluid and leukocytes from the blood into extravascular tissues. "Taken together, the current transcriptomic findings revealed anti-UC pharmacological targets, including the newly discovered biotargets CCL11, CCL21, CXCL3, and CXCR2, of mesalazine against DSS-induced intestinal inflammation." (PMID 34456974, 2021).
neurodegenerative disease (3 papers, 2022). A disorder of the central nervous system characterized by gradual and progressive loss of neural tissue and neurologic function. "Studies have shown that cytokines released from neurons, including CCL2, CCL21, HMGB1, CGRP, Substance P, CX3CL1, MMP2, and MMP9, can mediate microglia activation in brain injury, neuropathic pain, or neurodegenerative diseases." (PMID 36131309, 2022).
infectious disease (2 papers, 2014 to 2017). A disorder directly resulting from the presence and activity of a microbial, viral, or parasitic agent in humans. "Despite the fact that CCL19 and CCL21 are mainly produced in secondary lymphoid tissue, CCL19 and CCL21 production in non-lymphoid organs has been observed during inflammatory and infectious diseases." (PMID 29085362, 2017).
nephropathy (2 papers, 2016 to 2020). A nonspecific term referring to disease or damage of the kidneys. "On the other hand, the non-canonical activation of NFκB can promote the expression of CCL21 in podocytes; its expression being related to the progression of renal disease and proteinuria in rats." (PMID 32340145, 2020). "The in vivo observation of increased CCL21 and Fn14 expression in experimental proteinuric kidney disease suggests that this might be a clinically relevant observation." (PMID 27353019, 2016).
cardiovascular disease (1 paper, 2021). "Among both CCR7 ligands, CCL21 is of particular interest in our cohort because it is not only involved in the homing of cells to the endothelial venules in lymph nodes, thus alleviating leucocytic transmembrane trafficking, but it is also a putative marker of cardiovascular disease." (PMID 34941677, 2021).
colon polyps (1 paper, 2022). "The colon polyps demonstrated decreased expressions in CCL5, CCL18, CCL19, CCL21, CXCL12, CXCL14 and CXCL13 genes in this research." (PMID 35486660, 2022).
Lymph node (1 paper, 2021). "Lymph node metastasis was significantly reduced by the administration of mutant-CCL21 compared to the control." (PMID 34298676, 2021).
myopathy (1 paper, 2019). A disease of the muscle in which the muscle fibers do not function properly. "Positivity for CCL21 was seen in cases of PD-1 myopathy at the endothelial cells of the blood vessels, but also in the perivascular space and around some muscle fibers." (PMID 31533865, 2019).
neurological disorders (1 paper, 2021). "The current findings provide a theoretical and experimental basis, but the mechanisms of the hsa-miR-933/RELB/CCL21 regulatory axis in the development of HF and neurological disorders should be validated by cellular and animal experiments." (PMID 34595235, 2021). "Thus, hsa-miR-933, RELB, and CCL21 may be correlated with HF and neurological disorders." (PMID 34595235, 2021).
CCL21 also shares sentences with these, for which no sentence is quoted: adenocarcinoma (4 papers); pancreatic ductal adenocarcinoma (3); aortic aneurysm (2); cognitive disorder (2); Crohn disease (2); Hypertension (2); idiopathic pulmonary fibrosis (2); lupus (2); metabolic disease (2); metastatic cancer (2); neck cancers (2); ovarian carcinoma (2); preeclampsia (2); spinal cord injury (2); Stroke (2); synovitis (2); thyroid (2); abdominal aortic aneurysm (1); adult T-cell leukemia/lymphoma (1); Allergy (1); autosomal dominant polycystic kidney disease (1); bipolar disorder (1); brain disorder (1); Carcinoid (1); celiac disease (1); Cerebral ischemia (1); cervical squamous cell carcinoma (1); chronic graft versus host disease (1); chronic kidney disease (1); citrullinemia (1).
A further 58 diseases each share a sentence with CCL21 in 1 paper.